ELFN1-AS1 (ELFN1 antisense RNA 1)
Synonyms: MYCLo-2
Gene: Long non-coding RNA gene on chromosome 7 (1,738,624 to 1,742,317, reverse strand). Ensembl gene ENSG00000236081.
Diseases named in the same sentence as ELFN1-AS1 in open-access papers:
ELFN1-AS1 is named in the same sentence as 3 diseases in open-access papers, as found by Europe PMC text mining. Sharing a sentence is not in itself a finding about the gene and the disease. The quoted sentences say what the papers report.
colorectal cancer (2 papers, 2018 to 2025). A primary or metastatic malignant neoplasm that affects the colon or rectum. "The Solute Carrier Family 5 member 4 SLC5A4 Antisense RNA 1 (SLC5A4-AS1), Solute Carrier Organic Anion Transporter Family Member 1B3 (SLCO1B3), and ELFN1 Antisense RNA 1 (ELFN1-AS1) were identified as having an H3K4me3 peak in colorectal cancer cells but not in normal colon samples." (PMID 40141189, 2025).
ovarian carcinoma (1 paper, 2023). A malignant neoplasm originating from the surface ovarian epithelium. "ELFN1-AS1 (ELFN1 antisense RNA 1, also named MYCLo-2), is a newly discovered antisense lncRNA of ELFN1 that has a reported role as an oncogene in various solid tumors including esophageal and ovarian cancers as well as CRC." (PMID 37147528, 2023).
ELFN1-AS1 also shares sentences with these, for which no sentence is quoted: cancer (1 paper).